OR8K3 (olfactory receptor family 8 subfamily K member 3 (gene/pseudogene))
Description:
Odorant receptor.
Synonyms: OR11-181
Tractability: Antibody: its Gene Ontology location is reachable by antibodies, with high confidence; UniProt places it where antibodies can reach, with medium confidence; UniProt predicts a signal peptide or a membrane-spanning region.
Gene: Protein-coding gene on chromosome 11 (56,315,144 to 56,320,639, forward strand). Ensembl gene ENSG00000280314.
Subcellular location: Cell membrane
Pathways (Reactome):
Sensory Perception: Expression and translocation of olfactory receptors; Olfactory Signaling Pathway
Gene Ontology:
Molecular function: olfactory receptor activity; G protein-coupled receptor activity
Biological process: G protein-coupled receptor signaling pathway; sensory perception of smell; detection of chemical stimulus involved in sensory perception of smell
Cellular component: plasma membrane; membrane
Genetic constraint (gnomAD): Missense variants: 432 observed, 369.3 expected, observed/expected ratio (o/e) 1.17, 90% interval 1.08 to 1.27. Synonymous variants: 157 observed, 140.25 expected, observed/expected ratio (o/e) 1.12, 90% interval 0.98 to 1.28.
Homologues: Orthologues: chimpanzee OR8K3 (99% identical), dog OR8K54 (83% identical), mouse Or8k3 (83% identical), rat Or8k3 (82% identical), dog OR8K86 (81% identical), mouse Or8k3b (80% identical), dog OR8K87 (80% identical), dog OR8K7 (79% identical), mouse Or8k32 (78% identical), mouse Or8k22 (77% identical), rat Or8k32 (77% identical), mouse Or8k33 (77% identical), and 21 more. Paralogues in human: OR8K5 (69% identical), OR8K1 (68% identical), OR8J1 (58% identical), OR8J2 (58% identical), OR8J3 (58% identical), OR8U3 (57% identical), OR8U1 (56% identical), OR5AP2 (52% identical), OR5B12 (51% identical), OR5J2 (51% identical), OR8B12 (51% identical), OR8D1 (51% identical), and 84 more.
Diseases named in the same sentence as OR8K3 in open-access papers:
OR8K3 is named in the same sentence as 1 disease in open-access papers, as found by Europe PMC text mining. Sharing a sentence is not in itself a finding about the gene and the disease. The quoted sentences say what the papers report.
hepatitis B infection (1 paper, 2014). "HCC derived from hepatitis B infection demonstrated a significantly higher rate of OR8K3, PRL and RYR2 mutations (22% vs. 0%, 22% vs. 1%, 22% vs. 2%; p = 0.008, p = 0.022, p = 0.041, respectively)." (PMID 24988079, 2014).